LEPR (leptin receptor)
Diseases named in the same sentence as LEPR in open-access papers (continued):
Sharing a sentence is not in itself a finding about the gene and the disease.
cancer (108 papers, 2006 to 2026). A tumor composed of atypical neoplastic, often pleomorphic cells that invade other tissues. "Increased leptin and leptin receptor expression is associated with worse prognosis, increased morbidity, mortality, metastasis, and cancer recurrence." (PMID 34912237, 2021). "Accumulated experimental results have highlighted the role of leptin–leptin receptor signaling in promoting several processes linked to cancer progression, including cell proliferation, metastasis, angiogenesis and chemoresistance." (PMID 33799880, 2021). "In upper tract urothelial carcinomas, leptin receptor expression was associated with unfavorable prognosis for recurrence-free survival (p = 0.09) and cancer-specific survival (p = 0.01) by log-rank test." (PMID 33799880, 2021). "With LEPR loss, cancer cells exhibited a less aggressive phenotype, and macrophage recruitment was abolished; the phagocytic activity and cytokine production of macrophages also appeared to decrease." (PMID 33799880, 2021). "LEPR rs1137101 G>A polymorphism is located on the exon region of LEPR gene, and it has been thought to be involved in the development of cancer by a number of studies." (PMID 31196966, 2019). "We searched literature on the relationship of LEPR rs1137101 G>A polymorphism with cancer risk by using PubMed and Embase databases, covering all publications up to 14 October 2018." (PMID 31196966, 2019). "LEPR rs1137101 G>A polymorphism (Arg223Gln) is the most extensively studied association of this SNP with the development of cancer." (PMID 31196966, 2019). "Recently, variants in LEPR gene and their potential associations with cancer risk have been explored." (PMID 31196966, 2019). "Sample size was an important factor to determine the relationship between LEPR rs1137101 G>A polymorphism and cancer risk." (PMID 31196966, 2019). "The potential relationships of LEPR rs1137101 variants with susceptibility of cancer have been elucidated in different malignancies; however, the obtained results were inconsistent." (PMID 31196966, 2019). "A number of studies have focused on the association of LEPR rs1137101 variants with susceptibility of cancer, however, the observed results were controversial." (PMID 31196966, 2019). "Recently, more studies concerning the association of LEPR rs1137101 locus with cancer risk were performed." (PMID 31196966, 2019). "In this meta-analysis, 33 publications involving 44 independent case–control studies on the relationship of LEPR rs1137101 G>A polymorphism with cancer risk were recruited." (PMID 31196966, 2019). "The clinical association of leptin or leptin receptor with cancer patient outcome had been explored." (PMID 29682217, 2018). "Correlations between leptin levels and cancer have been described previously, while leptin signaling via LEPR has been implicated in breast and other cancers." (PMID 29212170, 2017). "The evidence of the association between LEPR rs1137101 G>A polymorphism and cancer risk was insufficient in Asians." (PMID 29312594, 2017). "Several case-control study focused on the relationship of LEPR rs1137101 G>A polymorphism and the risk of cancer." (PMID 29312594, 2017). "Numerous epidemiological studies have examined associations of genetic variations in LEP (G2548A, -2548 nucleotide upstream of the ATG start site) and LEPR (Q223R, nonsynonymous SNP in exon 6) with cancer susceptibility; however, the findings are inconsistent." (PMID 24146750, 2013). "Previous reports demonstrated that genetic variation in LEPR affected cancer susceptibility with significantly higher frequency of the LEPR 223Arg allele in patients than in controls; however, this association was not be replicated by later studies." (PMID 24146750, 2013). "Several studies have shown the relationship between LEP and LEPR gene polymorphisms and human cancer." (PMID 16504019, 2006). "The association of LEPR rs1137100 SNP with risk of cancer were inconsistent." (PMID 38659416, 2024).
cancer (continued). "Notably, both leptin and LepR are frequently altered in many obesity-associated cancers, including lung, breast, ovarian, pancreas, liver, and prostate." (PMID 37650871, 2023). "In addition, serum leptin and leptin receptor RNA expression showed a positive association with cancer recurrence and mortality in triple-negative breast cancer." (PMID 33799880, 2021). "Several studies have reported that leptin and leptin receptor are implicated in cancer, mainly via the JAK/STAT pathway, which regulates PI3K/AKT3 and ERK1/2 signaling, angiogenic factors (VEGF), systemic inflammation (TNF-α, IL6), and anti-apoptotic proteins (XIAP) expression." (PMID 34356668, 2021). "Several case–control studies reported that LEPR rs1137101 G>A polymorphism might be associated with the decreased risk of cancer." (PMID 31196966, 2019). "Hence, we carried out an updated meta-analysis on such relationship so as to further explore the role of LEPR rs1137101 variants to susceptibility of cancer." (PMID 31196966, 2019). "However, null associations of LEPR rs1137101 locus with cancer susceptibility was identified, which was analogous to the results reported in previous meta-analyses, but unlike the other four meta-analyses." (PMID 31196966, 2019). "In summary, this meta-analysis may be the largest sample size so far to assess the potential association of cancer risk with rs1137101 G>A polymorphism in LEPR gene." (PMID 31196966, 2019). "LEPR rs1137101 G>A polymorphism may alter the susceptibility of cancer by influencing the ability of binding with LEP." (PMID 29312594, 2017). "The LEPR Gln223Arg G allele and GG genotype have been reported to be linked with some cancers." (PMID 28368354, 2017). "However, studies are in conflict regarding which variant of the LEPR Gln223Arg polymorphism is associated with a higher risk of cancer." (PMID 26034683, 2014). "The LEPR Gln223Arg polymorphism, resulting in a change of glutamine to arginine at codon 223 in exon 6 of Receptor Leptin gene, has been associated with the development of and increased risk for cancer." (PMID 26034683, 2014). "Furthermore, polymorphisms in the LEP and LEPR genes have been associated with several cancer types, such as colon, prostate, and breast cancers." (PMID 26034683, 2014). "Subsequently, variants in LEPR were also found to influence cancer risk in Caucasian, directly." (PMID 23593308, 2013). "Meta-analysis of the association between LEPR Q223R polymorphism and cancer risk." (PMID 24146750, 2013). "Thus, the correlation of LEPR rs6588147 with the risk of cancer was conflicting." (PMID 38659416, 2024). "Additionally, LEPR rs12037879 might be associated with a marginal increase in CRC risk, influenced by smoking, cancer inheritance in the family, and LEPR rs6690625." (PMID 35563103, 2022). "Indeed, the expression of the leptin receptor (ObR) is a feature of cancer stem cells and its activation is able to regulate several signaling pathways and oncogenes, which are critically implicated in cancer stem cell activity." (PMID 32526957, 2020). "The growing list of leptin/leptin receptor targets has shortened the gap between our understanding of inflammation, metabolism and cancer and will offer novel avenues for drug intervention." (PMID 40095546, 2025). "Several functional SNPs of LEPR have so far been explored for their roles in contributing to the occurrence of cancer." (PMID 38659416, 2024). "To date, there is no other report that has found such a frequent occurrence of leptin receptor expression in CRC or any other cancer." (PMID 36981858, 2023). "LEP and LEPR were examined in BC tissues, benign breast tissues, para-carcinoma tissues using immunohistochemical staining." (PMID 36941557, 2023). "The high level expression of LEP and LEPR in BC tissues were significantly higher than that in benign breast tissues and in para-carcinoma tissues (all P < 0.05)." (PMID 36941557, 2023).
cancer (continued). "Based on the results, the rate of leptin receptor expression in carcinoma patients was significantly higher than the non-carcinoma samples." (PMID 37600567, 2023). "In conclusion, the positive rate of LEP and LEPR expression in BC tissues was significantly higher than that in benign breast tissues and normal para-carcinoma tissues." (PMID 36941557, 2023). "The leptin-leptin receptor signaling is also known to play a critical role in cancer progression, including cell proliferation, metastasis, angiogenesis, and chemoresistance." (PMID 36381236, 2022). "Rather, we uncovered a cancer link to the leptin–LEPR signalling pathway that becomes activated de novo downstream of an oncogenic HRAS(G12V)-induced change within otherwise normal skin stem cells." (PMID 36450983, 2022). "Hereby, we discuss in detail the oncogenic pathways that LEP, upon binding to its receptor LEPR is able to activate, thus promoting cell proliferation, migration, and angiogenesis, largely acknowledged as hallmarks of cancer." (PMID 36291602, 2022). "In cancer tissues, data suggest that LEPR activates similar oncogenic mechanisms and promotes glucose metabolism cell proliferation, angiogenesis, inflammation, and invasion." (PMID 36077676, 2022). "The protein LEPR, a member of the class 1 cytokine receptor family, has been suggested to play important roles in the pathogenesis of many malignant tumours, such as breast, colon, and prostate cancer." (PMID 33397392, 2021). "Leptin and leptin receptor are also involved in the development of various cancers like breast, thyroid, colon, and prostate cancers through pathways that promote proliferation, cell migration and invasion." (PMID 34356668, 2021). "MAPK signaling was activated to induce AP-1 binding to the VEGF-A promoter and initiate transactivation upon stimulation of the leptin-leptin receptor signaling axis in cancer cells." (PMID 33799880, 2021). "The Oncomine database analysis indicated that cancer tissues had a significantly higher expression level of LEPR than normal samples." (PMID 33397392, 2021). "The demonstrations of main biological effects and signaling axes induced by leptin/leptin receptor in different cancer types were shown." (PMID 33799880, 2021). "Several studies have been carried out to correlate enhanced leptin receptor levels with carcinogenesis and cancer progression." (PMID 32802842, 2020). "The researchers went on to explain that LEPR overexpression has a fundamental role in breast carcinogenesis, since it enables cancer cells to internalize circulating leptin." (PMID 33213024, 2020). "According to the Kaplan–Meier survival curves, the cancer survival rate in the LEPR gene between high- and low/medium-expression level groups in KICH patients was statistically significant (P = 2.10E − 04)." (PMID 33299884, 2020). "Since it has been reported that the leptin receptor plays a crucial role in maintaining cancers in a stem cell-like state, we investigated the effects of this cytokine on the stemness of GBM cells." (PMID 32526957, 2020). "Novel unpredicted interactions were found between leptin receptor, STAT3, and ABCB1, which has been linked to the development of drug resistance in cancer cells." (PMID 32471192, 2020). "Leptin acts as an adipocytokine functions via the leptin receptor, which stimulates growth, migration, and invasion of cancer cells." (PMID 32596369, 2020). "Cancer cells have been shown to produce leptin and leptin receptor (LEPR), which strongly indicates the existence of a leptin-induced signaling pathway in the proliferation of cancer cells." (PMID 32742493, 2020). "LEPR staining was observed in the cytosol and the nuclei of cancer cells and was significantly higher in the cytosol (§ p= 0.018); LEPR levels in the cytosol were high in 68% of the samples." (PMID 33213024, 2020).
cancer (continued). "According to the previous findings in publications and in silico analysis from the clinical cancer databases, the expressions of leptin and leptin receptor are found in many types of cancer." (PMID 29682217, 2018). "We relatively display leptin and leptin receptor expression levels in pan-cancer panel based on the transcriptome analysis via dataset The Cancer Genome Atlas (TCGA), and show the clinical association of the axis in predicting cancer prognosis." (PMID 29682217, 2018). "Polymorphisms in LEPR are reported to participate in the onset of T2DM, and rs3806318 and rs1327118 in LEPR are also identified to contribute to cancer and inflammatory response." (PMID 29301582, 2018). "MAPK signaling was activated to enhance AP-1 binding to VEGF-A promoter for transactivation by leptin-leptin receptor axis in cancer cells." (PMID 29682217, 2018). "In this review, we focus on the pathological function of leptin-leptin receptor in cancer, and further illustrate the clinical significance based on the correlation with cancer patient outcomes." (PMID 29682217, 2018). "Leptin receptor appears to be expressed in various types of cancer, suggesting the leptin axis function other than appetite regulation." (PMID 29682217, 2018). "There was a difference in the LEPR rs6588147 G>A polymorphism between overall ESCC patients and non-cancer controls." (PMID 29312594, 2017). "Several studies have indicated that LEPR signaling can induce cancer cell adhesion, angiogenesis, proliferation, survival, migration and stem cell-ness in several malignancies." (PMID 29212170, 2017). "The TCF7L2 rs7903146 C>T, rs290481 T>C, LEP rs7799039 A>G, rs2167270 G>A and LEPR rs1137100 G>A, rs1137101 G>A and rs6588147 G>A polymorphisms were genotyped by SNPscan genotyping assays in 507 ESCC cases and 1,496 non-cancer controls." (PMID 29312594, 2017). "LEP combines to LEPR and exerts its important roles in the development of metabolic disorders and malignancies." (PMID 29312594, 2017). "As one of explanations for that leptin-receptor expression group showed poor survival rate of patients, we suggest that leptin-receptor counteracts apoptosis in cancer cells, since leptin-receptor inhibition induced an increased apoptosis in the present study." (PMID 26147886, 2015). "Binding of leptin to its receptor LEPR-Long elicits a proliferative and angiogenic signal transduction cascade, which varies remarkably depending on cancer cell types." (PMID 25482303, 2014). "In two-way interaction analyses, we found that LEPR rs12037879 presented significant interactions with smoking status and family history of cancer." (PMID 23593308, 2013). "Consistently, a significant factor-dosage effect was detected among LEPR rs12037879, LEPR rs6690625, smoking status and family history of cancer." (PMID 23593308, 2013). "Since LEPR rs12037879, rs6690625 presented significant two-way interactions with smoking status and family history of cancer, we further detected multifactor interactions among these factors." (PMID 23593308, 2013). "In some cancer cells, expression of leptin receptor levels and stimulation by leptin will lead to increase of cell proliferation." (PMID 22007338, 2011). "Our recent study indicated that leptin and the leptin receptor (ObR) were significantly overexpressed in primary breast cancer and lymph node metastasis relative to non-cancer mammary epithelium." (PMID 20569445, 2010). "Both functional studies and genetic analyses have highlighted the role of LEP and LEPR in cancer pathogenesis and disease progression." (PMID 16504019, 2006). "The role of LEPR rs1137101 in the development of cancer has been studied." (PMID 38659416, 2024). "The presence of leptin also stimulates leptin receptor expression in cancer cells." (PMID 38238841, 2024).
cancer (continued). "The leptin receptor, a type 1 cytokine receptor, has been shown to be highly abundant in a broad range of cancer types with an important role in the escalation and pathogenesis of many tumors via activation of signaling cascades crucial for cancer cell growth." (PMID 38418632, 2024). "In addition, overexpression of the leptin receptor has been observed in cancer tissues compared to normal tissues, particularly in cancers with an aggressive phenotype or drug resistance." (PMID 38238841, 2024). "Indeed, leptin and the leptin receptor are usually overexpressed in cancer patients, wherein this adipokine stimulates proliferation, migratory and invasive potential, and stemness capabilities in the multiple types of tumors here discussed." (PMID 37509120, 2023). "To examine whether the effect of circulating miR-204 on thermogenesis and lipolysis-mediated leptin signalling pathway, we employed the db/db mice lack leptin receptor to examine the effect of cancer-derived miR-204 on thermogenesis and lipolysis in WAT." (PMID 37620316, 2023). "The LEPR rs1137101 (Arg223Gln), a missense SNP, has been analyzed for the correlation with cancer risk and development; however, the previous results were not consistent." (PMID 35223490, 2022). "These unique ‘loose’ binding characteristics of EREG with EGFR might facilitate its binding with LepR, increasing glucose influx in normal and/or cancer cells." (PMID 35159237, 2022). "In addition, leptin receptor was characterized to be expressed in various types of cancer, suggesting biological functions for leptin outside of appetite regulation." (PMID 33799880, 2021). "Leptin Receptor (LEPR) has been suggested to have several roles in cancer metastasis." (PMID 33397392, 2021). "LEP binds to mutant LEPR that altered Gln to Arg leads to changes in LEP signaling in the genetic expressions of the key cancer genes and consequently might exposed to the possibility of the breast, lung, oral, and colon cancer." (PMID 33369452, 2020). "In addition, we examined significant relationships between the mRNA co-expression of FGFR1 and LepR in 29 primary cancers." (PMID 33019728, 2020). "It seems that while the LEPR pathway has much potential to be a target for anti-cancer drug therapy, drugs might be better targeted to particular variants of LEPR." (PMID 31592340, 2019). "Then, we investigated whether the effects of leptin on FAK and Src activation and the enhanced migratory capabilities of cultured cancer cells were mediated by the canonical leptin-receptor signaling pathway." (PMID 31671408, 2019). "The results showed the relative leptin and leptin receptor expression in pan-cancer panel." (PMID 29682217, 2018). "Furthermore, the correlation of leptin and leptin receptor with cancer patient's survival outcome is listed." (PMID 29682217, 2018). "In addition to the original function in controlling appetite and energy expenditure, leptin-mediated signaling axis through leptin receptor is multifunctional which plays role in the regulation toward broad types of cancer." (PMID 29682217, 2018). "Furthermore, the increased serum leptin and leptin receptor mRNA expression revealed the positive correlation with cancer recurrence and mortality in triple-negative breast cancer." (PMID 29682217, 2018). "In agreement with previous data demonstrating that leptin receptor plays a crucial role in maintaining cancers in a stem cell-like state, we found that MCF-7 mammosphere cultures exhibited increased OBR mRNA expression and in a greater extent the long isoform, compared to monolayer cells." (PMID 26556856, 2016). "Antiapoptotic effect of leptin-receptor has been described in other human cancers." (PMID 26147886, 2015). "Leptin receptor antagonists, Aca 1 (aa 121–129; modifications Nva123, Aca129) and Allo-aca (aa 121–129; modifications alloThr121, Nva123, Aca129) have been shown to inhibit leptin-dependent growth and signaling in various cancer cells." (PMID 26359358, 2015).